ENSG00000273154 (novel protein, ZGPAT-LIME1 readthrough)
Gene: Protein-coding gene on chromosome 20 (63,708,864 to 63,739,103, forward strand). Ensembl gene ENSG00000273154.
Genetic constraint (gnomAD): Loss-of-function variants: 17 observed, 15.56 expected, observed/expected ratio (o/e) 1.09, 90% interval 0.75 to 1.63. The synonymous counts are far from expectation, so gnomAD's model fits this gene poorly and the ratio says little. Missense variants: 408 observed, 329.89 expected, observed/expected ratio (o/e) 1.24, 90% interval 1.14 to 1.34. Synonymous variants: 190 observed, 144.95 expected, observed/expected ratio (o/e) 1.31, 90% interval 1.16 to 1.48.